SOX2 (SRY-box transcription factor 2)
Diseases named in the same sentence as SOX2 in open-access papers (continued):
Sharing a sentence is not in itself a finding about the gene and the disease.
tumor (continued). "In addition, SOX2 also plays an important role as an oncogene involved in the growth capacity of tumor stem cells." (PMID 37888115, 2023). "In a mouse model of Shh-MB, cells expressing Sox2 accounts for a proportion of less than 5% of the total tumor cells but might serve as a reservoir for relapse." (PMID 37596267, 2023). "Sox2, a stem-cell transcription factor, was upregulated over the course of the 7 days in suspension culture relative to monolayer controls, which is necessary for the tumor sphere formation of BCC lines." (PMID 36979915, 2023). "Next, We tested whether the small molecule RepSox that is able to replace Sox2 in cellular reprogramming is able to inhibit Kras-induced tumor formation." (PMID 37882674, 2023). "Lin28B-let-7 pathway positively regulates the expression of stemness factors Oct4 and Sox2; it causes a switch of non-CSCs to CSCs with tumor starting and self-renewal characteristics in oral CSC." (PMID 37065869, 2023). "In addition, we showed that GSCAR activates the self-renewal ability of GSCs by mediating DHX9 and IGF2BP2 complex formation, leading to the stabilization of the SOX2 transcript and tumor growth." (PMID 37063420, 2023). "Another study also revealed that METTL3 promotes tumor progression by maintaining SOX2 expression." (PMID 37151889, 2023). "Furthermore, the postnatal deletion of LATS1 and the subsequent upregulation of the YAP/TAZ promoted the uncontrolled growth of the SOX2 pituitary stem cells and tumor formation, resembling pituitary cancer." (PMID 37109772, 2023). "Further, Oct-4 and Sox2 activate cancer stem cells or tumor-initiating cells in some contexts." (PMID 38020885, 2023). "As reported in representative images and relative histograms, SOX2 knockdown significantly reduced the number of tumor spheroids from a mean of 164.21 to 139.81 in CAL27 and from 200.15 to 147.65 in SCC15 cells (*p-value < 0.05, CAL27) (**p-value < 0.01, SCC15)." (PMID 38096163, 2023). "Similarly, SOX2-positive cells were predominantly located in regions containing the tumor, and both the prevalence of SOX2-expressing cells and their SOX2 expression levels declined dramatically or were undetectable in the outer areas." (PMID 37058447, 2023). "Indeed, another independent research showed that FoXO1 accumulation in BC cells promoted the expression of SOX2, a transcription factor related to the tumor stem cell phenotype." (PMID 36901916, 2023). "In addition, epigenetic alterations, including the overexpression of epigenetic modulators such as EZH2 and SOX2, seem to be involved in tumor evolution as components of lineage plasticity." (PMID 37686633, 2023). "Our discovery that enhancers involved in the development of the digestive and respiratory systems are reprogrammed to support SOX2 up-regulation during tumorigenesis is in line with previous observations that tumor-initiating cells acquire a less differentiated phenotype." (PMID 37738673, 2023). "Decreased SOX2 expression in the DZ-CIS treated group could be related to the decrease in the tumor stem cell population." (PMID 37268911, 2023). "SOX9/SOX2/OCT4 are the key regulators of tumor stemness maintenance." (PMID 37143164, 2023). "Moreover, SOX2 has been shown to be essential for the survival and proliferation of OS cells in a mouse tumor model." (PMID 37957698, 2023). "The MuAPT and (-/-sox2) cohorts demonstrated a decrease in tumor cell and stemness marker staining." (PMID 36284815, 2022).
tumor (continued). "In line with CTCDOs enhanced aggressiveness and tumor-forming capacity, we found an increased expression of several factors implicated in stemness maintenance both in normal and malignant tissues such as PDX1, Goosecoid, Oct3/4, SOX2, DLL1, Cited-2." (PMID 35260172, 2022). "OCT4 and SOX2 expressions in tumor tissue and paired adjacent tissue." (PMID 35402219, 2022). "SOX2 can be utilized as the primary regulator of tumor squamous cell differentiation." (PMID 36056339, 2022). "Moreover, dual treatment induced a significant reduction of cell proliferation (Ki67 IHC) and amount of SOX2 positive tumour cells, while Caspase 3 cleavage was increased." (PMID 35473984, 2022). "Similar to KLF4, the biological impact of SOX2 in tumor cells is dependent on tumor type." (PMID 36553636, 2022). "Sox-2: Aberrant expression of Sox-2 can play a vital role in cancer progression by affecting the signaling pathways involved in tumor initiation, cell proliferation, epithelial-to-mesenchymal transition (EMT), migration, invasion, CSC regulation, and resistance to apoptosis and therapy." (PMID 36077751, 2022). "Similarly, it is likely that the stage at which SOX2 levels rise during tumor progression is likely to vary by cancer type." (PMID 35454854, 2022). "This analysis was designed to investigate whether SOX2 expression might predict the behavior of the tumor." (PMID 36232992, 2022). "SOX2 upregulation impaired the inhibitory effects of IR on tumour growth." (PMID 35415876, 2022). "HM+ tumor cells showed characteristics consistent with CSCs, neurosphere formation, and expression of the stem cell markers Sox2." (PMID 35798319, 2022). "Quantification of cells revealed that SOX2+Nestin+ cells were significantly more abundant within the tumor bulk compared to the peritumor area (P = 0.01) whereas CD105+ Nestin+ cells were found dispersed without any significant difference in the density of distribution between the two regions." (PMID 36038950, 2022). "A recent study showed that SOX2 expression correlated with a shorter time to metastasis and decreased survival after biochemical recurrence in a case-control cohort study of 1028 annotated tumor specimens." (PMID 35884514, 2022). "There is ample evidence that SOX2 levels rise during tumor progression in some cancers." (PMID 35454854, 2022). "Specifically, a study uncovered that Cyclin G1 up-regulates the expression of SOX2 by activating the Akt/mTOR signaling pathway, which leads to an increased proportion and enhanced tumor-initiating capacity of liver TICs, as well as inducing chemoresistance of HCC cells to sorafenib." (PMID 35267473, 2022). "In this C57BL/6 xenograft model, SOX2 absence also notably repressed tumour growth." (PMID 35415876, 2022). "In this regard, we observed that TCFL5 negatively regulates SOX2 in human tumor cells." (PMID 35768632, 2022). "Notably, SOX2 was pervasively expressed in tumor cells, which is consistent with the previous study." (PMID 35669791, 2022). "Examination of lineage-specific marker expression revealed four principal clusters corresponding to tumor and glia (using the SOX2, OLIG2, GFAP markers), lymphoid cells (CD45, CD3, CD8, and CD4), myeloid cells (CD45, PU.1, CD163, CD68, and CD11b), and endothelial cells (CD31)." (PMID 35973991, 2022). "Additionally, the expression of transcription factors known to promote tumor stemness (SOX2, OCT4 and NANOG) were significantly downregulated in DCIS cells expressing IPW and rescued when ID2 was expressed." (PMID 35078502, 2022). "CD44 is expressed in CSC, as well as in a variety of normal stem cells, and plays an important role in CSC self-renewal and proliferation, leading to tumor growth, tumor metastasis, the activation of stemness transcription factors such as Nanog, Sox2, and Oct4, and chemotherapy resistance." (PMID 35456011, 2022).
tumor (continued). "Overexpression of pluripotency genes, including c-Myc, SOX2 and Oct3/4, could promote the cancer stem cells and contribute to the tumor progression." (PMID 35473511, 2022). "High grades were populated by substantial proportions of SOX2-positive tumor cells." (PMID 36232992, 2022). "In PCPs the mechanism by which BRAFV600E mutation is oncogenic has not yet been fully understood but it may give both a proliferative advantage to tumor SOX2+ stem cells and impair their differentiation potential." (PMID 35757402, 2022). "Given that its Hub Gene is an indicator of SOX2, which is involved in the development and maintenance of stem-like properties in cancer cells, we considered that TBC1D8 may also be associated with tumor cell stemness." (PMID 35918393, 2022). "In addition, IHC staining demonstrated that downregulation of FAM64A decreased the expression of Ki-67, CD44, and SOX2 in tumor tissues." (PMID 35538067, 2022). "Besides, tumor OCT4 expression was associated with higher T stage, TNM stage, and poor differentiation, while SOX2 expression was correlated with elevated T stage, N stage, TNM stage, and poor differentiation." (PMID 35402219, 2022). "In this study, we found that there exist numerous CD105+ cells outside of the tumor border but very few SOX2+ Nestin+ cells which may be considered as the main tumor cell component in patient peritumoral samples." (PMID 36038950, 2022). "We have argued that increases in the levels of SOX2 can contribute to tumor growth, provided the increases in SOX2 are accompanied by changes in the expression of other genes that are able to counter the growth inhibitory effects of increased SOX2." (PMID 35454854, 2022). "Besides mammosphere generation, CTH-B544 and CTH-B693 gained a stemness phenotype with increased expression of Oct4, SOX2, and Nanog promoting tumor progression; CTH cells were positively stained for SSEA4 which is associated with EMT and drug resistance." (PMID 36077806, 2022). "Importantly, inhibition of SOX2 suppresses proliferation and invasion of breast cancer cells, inducing cell apoptosis in vitro and inhibiting tumor growth and metastasis in vivo." (PMID 35205716, 2022). "Altogether, our work and that of other groups strongly suggest that tumor cells hijack the growth inhibitory effects of elevated SOX2, consequently generating a reservoir of slowly cycling, drug-resistant tumor cells that can resist chemotherapy and drive disease recurrence." (PMID 35454854, 2022). "An increase in SOX2 activity enhances the proliferation of tumor cells." (PMID 36142766, 2022). "In addition, SOX2 dampened anti‐tumour immunity through inhibition of stimulator of interferon genes (STING) signalling, which is critical for the induction of type I IFN and stimulation of both innate and adaptive immunity." (PMID 35415876, 2022). "In addition, SOX2 OE potentiates tumor aggressiveness through the enhanced migration and invasion capacity of OC cell lines and increases tumor size in in vivo models." (PMID 35162954, 2022). "Moreover, this study showed the requirement of SOX2 for OS formation and survival of the tumor cells, proposing that disruption of these pathways initiated by SOX2 is an attractive strategy for the treatment of OS." (PMID 36551696, 2022). "In conclusion, KTN1-AS1, induced by SOX2, acts as a tumor-promoting gene and may serve as a potential therapeutic and prognostic biomarker for ESCC." (PMID 36418920, 2022). "Highly activated levels of SOX2 might also induce the reduction of tumor growth through its molecular rheostat function." (PMID 36038612, 2022). "SOX2 is a transcription factor that regulates cancer stem cell properties, as it can bind and activate regulators of stem-like tumor-propagating cells that are involved in tumor progression and therapeutic resistance." (PMID 35701472, 2022).
tumor (continued). "The striking effects of dual FMOD and SOX2 silencing on metastasis suggest that FMOD-regulated tumor–host interactions might be coupled with SOX2-driven signaling mechanisms in our model." (PMID 35737114, 2022). "We found that there was higher expression of Sox2 in tumor tissue than in normal tissues." (PMID 34976166, 2022). "In addition, as expected, these cells, which expressed stemness markers (e.g., Nanog, OCT4, and Sox2), were able to form spheroids in vitro and exhibited the properties of tumor-initiating cells in preclinical mouse models." (PMID 35582537, 2022). "For example, the overexpression of Gli1, a key protein in the Hh pathway, is considered as a symbol of Hh pathway activation and is able to activate oncogene target genes such as Cyclin-D1, Myc, Bcl-2, Ang1/2, Snai1, Nanog, and Sox2 to promote carcinogenesis and tumour development." (PMID 36358596, 2022). "SOX2 is also involved in multiple tumor cell functions, such as the promotion of tumor cell proliferation, the ability to repress apoptosis, acceleration of cell invasion and migration, and regulation of self-renewal in tumor stem cell populations." (PMID 35055392, 2022). "These two studies outline critical roles for Sox2 in tumor initiation and stemness in cSCCs." (PMID 35892887, 2022). "We then identified 4924 tumor cells (63.7% of the total cell population), characterized by a chromosome 7 gain and chromosome 10 loss, via inference of single-cell CNV state 5,10,11 and gene expression markers SOX2, PTPRZ1, and EGFR." (PMID 35941215, 2022). "We proposed that the tumor behavior and inflammatory condition might affect the amount of SOX2 expressing cells within a tumor." (PMID 35055392, 2022). "Additionally, we observed a slightly increased tumor incidence (22%) and significantly decreased latency (average age of 27 weeks) in Sox2-creERT2 compared to Sox2-cre mice (average age of 41 weeks)." (PMID 35318328, 2022). "Our results showed SOX2 silencing significantly decreased proliferation of GBM cells, so SOX2 overexpression may contribute to tumour progression of GBM." (PMID 34953010, 2022). "Moreover, we checked the PCAT1 and SOX2 expression in the tumour tissues, and the quantitative real‐time polymerase chain reaction (qRT‐PCR) results suggested that PCAT1 depletion downregulated SOX2 in vivo as well." (PMID 35415876, 2022). "Similarly, the increase in SETD1A expression in tamoxifen-resistant cells seems to be the result of the dominant survival of resistant clones, CSCs, expressing high levels of SETD1A and SOX2 due to intra-tumor heterogeneity in primary BC." (PMID 35966598, 2022). "More importantly, SOX2 promotes tumor tumorigenesis and progression." (PMID 36246971, 2022). "Furthermore, YAP1 promoted tumor stemness maintenance partly by acting as a transcriptional coactivator to promote TEAD2-induced SOX2 expression." (PMID 35864972, 2022). "Given the significant clinical challenge posed by drug-resistant, slowly cycling tumor cells, understanding the molecular mechanisms through which elevated SOX2 induces this state should help identify therapeutic targets that will enable the eradication of these cells." (PMID 35454854, 2022). "Consequently, the specific immunosuppressive roles and mechanisms of SOX2 in different tumor types remain to be elucidated." (PMID 35267473, 2022). "Further, we found that inhibition of UPF1 suppressed the malignant phenotype of ECSCs by destabilizing the oncogene LINC00963, which acted as an endogenous competition RNA (ceRNA) to prevent the tumor suppressor miR-508-5p from binding to the 3′UTR of SOX2 mRNA." (PMID 35318304, 2022). "Tumor tissues were enriched in Sox2, Oct-4 and Nanog mRNA transcripts." (PMID 35892887, 2022). "Upregulation of both Ki67 and SOX2 within the same marginal areas of the tumors is indicative of a highly proliferative and invasive tumor cell phenotype and suggests that VCAM-1 upregulation is closely associated with the invasive front of the tumor." (PMID 35312755, 2022).
tumor (continued). "Moreover, a lower sphere formation rate, higher apoptosis rate, lower tumor formation rate and longer survival time after temozolomide treatment were detected in the Sox2 knockout cells." (PMID 34976166, 2022). "MiR142-3p mimics could block IL-6, HMGA2, and SOX2 expression in GBM tumor cells that inhibit tumorigenicity." (PMID 35572545, 2022). "Tumor locations in these mice were comparable to those observed in Sox2-cre::Smarcb1fl/+ mice." (PMID 35318328, 2022). "The SOX2 silencing group's tumour size was lesser than that in the LV‐sh‐NC group." (PMID 35415876, 2022). "Interestingly, results of the real-time PCR also revealed increased expression of the Nanog, Oct4, Sox2, and Bmi1 mRNA transcripts (markers of the tumor-initiating cells) in the drug resistant cells." (PMID 34681918, 2021). "Double immunohistochemical staining on two of the mHNcSCC tissue samples showed expression of angiotensinogen by the SOX2+ CSCs within the tumor nests (TNs), and immunofluorescence showed expression of PRR and AT2R by the SOX2+ CSCs within the TNs and the peritumoral stroma (PTS)." (PMID 33513805, 2021). "Tumor development was unaffected by the mosaic deletion of one copy of Sox2 in p27−/− melanotrophs." (PMID 33574062, 2021). "Since inflammation is a key determinant of a pro-tumorigenic environment, it is perhaps unsurprising that the inflammatory mediator PGE2 drives expansion of multiple CSC populations (expressing LGR5, CD133, CD44, and SOX2) and promotes liver metastasis in orthotopic tumour models." (PMID 33673710, 2021). "Combination of these results indicated that PAK2 overexpression might perform its tumor-promoting efficacy through increasing the phosphorylation of SOX2." (PMID 34621737, 2021). "However, IHC staining demonstrated ubiquitous staining of SOX2 throughout the nucleus and cytoplasm of tumor cells, and in the nucleus of stromal cells." (PMID 34685477, 2021). "This SOX2-inducible model system could be exploited to determine the molecular mechanism by which elevation of SOX2 halts tumor growth." (PMID 35054230, 2021). "This study also demonstrated that the Sox2+ cell population expressing Aldh1a1, a protein associated with a cancer stem cell phenotype, generated tumours in vivo, while this capacity decreased with lower or absent expression of Aldh1a1." (PMID 34445233, 2021). "First, in the inducible model, it has been shown that the expression of oncogenic β-catenin in SOX2 + pituitary stem cells at different ages results in a significant reduction in tumour formation when comparing induction in aged (6–9 months old) vs. young (4–6 weeks old) mice." (PMID 34019103, 2021). "SOX2 is also highly expressed in ACC, being tightly associated with the clinical outcome of ACC and, therefore, it has been suggested to have utility as a prognostic marker in this tumor type." (PMID 35048028, 2021). "SOX2 is amplified in certain cancers and can drive clonogenic tumor growth." (PMID 34199293, 2021). "Indeed, previous in vivo studies have shown that Sox2 overexpression, together with the inactivation of tumor suppressors such as Pten or Lkb1, drives the formation of mouse lung squamous cancers." (PMID 34880227, 2021). "Together, our GBM data suggest that BTK protein may be expressed in SOX2-positive tumour cells, CD163-positive macrophages, and a third population of cells which needs further characterisation." (PMID 34645618, 2021). "We identified 16 tumor samples with tandem duplications at the SOX2-e1 region." (PMID 34880227, 2021). "The high expression of SOX2 in the COSCC invasive front and tumor “budding” corresponds to its aggressive biological behavior, but the increased presence of SOX2-positive cells in outer layers of the CAA epithelium is surprising and further investigation of the fate of these cells is needed." (PMID 34072517, 2021). "The advance of tumor grade, was related to the increasing of SOX2 and CD133 cells." (PMID 34805277, 2021).